MET (MET proto-oncogene, receptor tyrosine kinase)
Diseases named in the same sentence as MET in open-access papers (continued):
Sharing a sentence is not in itself a finding about the gene and the disease.
cancer (continued). "The HGF/MET axis was reported as a potential key contributor to promoting chemoresistance in cancer cells." (PMID 37175439, 2023). "Physiological HGF/MET signaling is relevant for mammalian development and tissue regeneration, although the same pathway is frequently dysregulated in cancer." (PMID 37170152, 2023). "MET overexpression was discovered to be one of the first mechanisms of dysregulation of MET; since its discovery, it has been detected in a variety of cancers." (PMID 37296895, 2023). "Genomic profiles of cancer patients identified that tumor-induced mutations in KRAS, STK11, KEAP1, CDKN2B, CTNNB1, and MET are significantly associated with cancer-associated thrombosis." (PMID 37046748, 2023). "In a broader context, the intricate interplay between the mTOR axis and MET biology underscores the pivotal role of translational regulation in governing MET expression within the realm of cancer." (PMID 37760640, 2023). "By combining in silico, in vitro, and in vivo findings, we aim to have a sharper picture of MET alterations in cancer and their biological significance, opening new avenues for targeted therapies." (PMID 37760640, 2023). "Altogether, we describe the ‘flare’ effect as the consequence of a strategy of cancer cells enhancing both MET phosphorylation (activation) and MET synthesis." (PMID 36697438, 2023). "HGF secreted by CAF binds to receptor tyrosine kinases to further activate the MET pathway, enhancing the crosstalk of cancer cells and hepatic stellate cells, resulting in cancer cells’ resistance to chemotherapy." (PMID 37035187, 2023). "MET-amplified tumors represent 4%, where MET overexpression is observed in more than 50% of cancers." (PMID 37760640, 2023). "In the present study, we show that the previously unreported phosphorylation of MET Serine 1016 is induced upon irradiation in cancer cell lines of various origins." (PMID 37188738, 2023). "MET is a clinically relevant cancer-related target but the determination of MET amplification and overexpression remains challenging." (PMID 37170152, 2023). "An ASP-driven chimeric transcript (L1-MET) between L1 and the receptor tyrosine kinase MET gene, which functions as an oncogene in many forms of cancer, has been observed in HCC." (PMID 38136578, 2023). "Dysregulation of MET signaling has been found in a variety of cancers through different mechanisms, such as activating point mutations of the MET gene, overexpression of the ligand HGF, MET gene copy number gain (MET-CNG)/amplification, and MET gene fusions." (PMID 36765572, 2023). "Among the ligands, this compound (1,2-benzenedicarboxylic acid) exhibited the highest binding affinity, particularly with crucial cancer-related genes, including MET, EPCAM, PTEN, and CHEK2." (PMID 38116103, 2023). "In this study, we addressed this gap by characterizing MET fusions in a large, real‐world Chinese cancer population." (PMID 37326363, 2023). "In this study, we applied CRISPR-Cas9 mediated knocking-out of the MET gene in cancer cells to cast light on the role played by the HGF/MET axis as a key regulator of cell-autonomous metastatic properties." (PMID 37345079, 2023). "Treatment with AXL and MET inhibitors successfully abolished Galectin-1 overexpression–mediated cancer stemness." (PMID 37433225, 2023). "In this context, MET ablation in cancer cells allows the role of MET to be explored only in the context of ‘the seed’, removing both intrinsic and extrinsic seed features." (PMID 37345079, 2023). "Cancer cells adopt this shrewd dual strategy to increase MET total protein quantity and MET phosphorylation (activation), leading to a rapid resumption of cancer cell proliferation." (PMID 36697438, 2023). "It is also possible that HGF detected in the cancer cells is produced in the stroma but bound on MET at the plasma membrane or in the cytoplasm after internalisation." (PMID 36799689, 2023).
cancer (continued). "In line with this, we developed an auto-updatable ‘MET observatory’ to catalogue genetic alterations of the MET gene in cancer." (PMID 37760640, 2023). "Dysregulated c-MET activation drives cancer cells to survive, proliferate, and metastasize, and is linked to undesirable clinical outcomes." (PMID 37924112, 2023). "Mutations in STK11, CDKN2B, KEAP1, CTNNB1, MET, and KRAS were associated with a significantly increased risk of cancer-associated thrombosis." (PMID 38069251, 2023). "The results demonstrated a significant increase in cancer cell migration over the wound, providing further evidence that MET collaborates with NMDAR2B to promote cell migration." (PMID 38201232, 2023). "In the same cancer tissues, the MET pathway frequently interacts with other receptor tyrosine kinases (RTKs), including EGFR." (PMID 37692610, 2023). "The signaling pathway of HGF/c-MET has been investigated in many solid cancer types, as it is considered an important target in the diagnosis, prognosis, and treatment of cancer." (PMID 36789987, 2023). "It will be important to assess the generality of MET inhibitors in apparently suppressing LMRS metabolism in carcinomas." (PMID 37762668, 2023). "Aberrant HGF/MET pathway plays as an oncogenic driver, since dysregulation of c-MET and HGF has been implicated in cancer pathogenesis as it is involved in the mechanisms of cell proliferation and survival, invasion, and metastasis." (PMID 35069735, 2022). "The differences in the expression of low/high c-MET in normal and cancer tissue counterparts were highly statistically significant." (PMID 36498560, 2022). "Its expression is regulated by hypoxia and cell stress, and its kinase activity is induced by several growth factor receptors implicated in cancer including members of the ERBB family, IGFR1, and MET." (PMID 36158685, 2022). "PD-L1 induction triggered by c-MET is involved primarily in cancer immune escape through the PD-1/PD-L1 pathway." (PMID 35069735, 2022). "c-Mesenchymal-epithelial transition (c-MET), an HGF receptor, has been shown to play a decisive role in therapy resistance in various cancers." (PMID 35693705, 2022). "Subsequently, MET/HGF-dependent nitric oxide release by neutrophils assists in cancer cell killing, which greatly dampens tumor growth and metastasis." (PMID 35784290, 2022). "Transcriptomic classification of cancer cell lines based on MET expression showed that response to the PARP inhibitor (PARPi) olaparib is poorer in MET overexpressing cell lines." (PMID 35628590, 2022). "Remarkably, we identified mTOR, BLM, MET, AMPK, and p130 as new SMYD3 interactors implicated in cancer processes." (PMID 35495117, 2022). "In preclinical models, c-MET expression levels were higher in poorly differentiated and invasive cancer cell lines." (PMID 36498560, 2022). "Currently, several small-molecular inhibitors and antibody-based drugs targeting MET are under development as potential therapeutics for different cancer indications, but so far, only a few of these have obtained regulatory approval and reached the clinic." (PMID 35565287, 2022). "In lung carcinoma, EGFR- or MET-expressing cancer cells exhibited an elevated glycolysis activity and increased production of lactate that induced CAFs to secrete large amounts of HGF through an NF-κB-dependent mechanism." (PMID 35814444, 2022). "When we searched the database, we found a correlation between c-MET and cancer migration and invasion (P < 0.01)." (PMID 35874635, 2022). "HGF and MET are aberrantly upregulated in various cancers, such as breast and esophageal cancers, hepatocellular carcinoma, and non–small cell lung cancer." (PMID 35085554, 2022). "Pro-oncogenic proteins, such as Src, SMO and c-MET, localize in lipid rafts and initiate signaling transduction, indicating potential involvement of lipid rafts in cancer progression." (PMID 35303882, 2022).
cancer (continued). "Data from preclinical studies, including cellular models of lung, colorectal, and gastric cancers, indicate that the MET pathway is vital for the growth, survival, and invasive potential of cancers." (PMID 35402233, 2022). "In the pediatric population, tivantinib has been investigated as a c-MET inhibitor in multiple cancer types." (PMID 36034555, 2022). "Cytoskeletal remodeling and reorganization are known to cause the major processes of cancer movement and metastasis, and the HGF/c-MET signaling route plays a critical role in cancer metastasis." (PMID 35630066, 2022). "As OSCC patients falling in the third category developed cancers that are positive for the protein’s catalytic domain, they are likely to be eligible for MET-targeted therapies." (PMID 35326642, 2022). "c-MET has been a well-studied target for cancer treatment and numerous targeted inhibitors have been developed." (PMID 36209270, 2022). "By contrast, in vitro studies have identified alterations in MYC, mTOR, and PIK3CA, but notably rarely KRAS alterations, as potential drivers of resistance in MET-addicted cancer cells with MET-amp." (PMID 35326531, 2022). "The results indicated that the expression levels of TSC1, ITGA6, and MET in most cancer cell lines (SW1990, PANC1, Mia-paca-2, CFPAC1) were significantly higher than those in the normal cell line (H6C7)." (PMID 36261830, 2022). "In cancer, the interplay between MET and other RTKs, either through RTK coactivation or RTK switching, has profound implications in the mechanisms of resistance to anticancer chemotherapy." (PMID 35269415, 2022). "Dysregulated expression of HGF/c-MET acts as a catalyst in many cancers, with overexpression of HGF often leading to aberrant cell proliferation and extracellular matrix invasion." (PMID 35778602, 2022). "qRT-PCR was performed to detect the relative expression levels of TSC1, ITGA6, and MET in normal and cancer cell lines." (PMID 36261830, 2022). "This HGF, in turn, activates MET-dependent signaling within cancer cells, counteracting the effects of tyrosine kinase inhibitors (TKIs)." (PMID 35326670, 2022). "The effect of Nb density on the binding and uptake of PEGylated liposomes was tested in MET-positive and MET-negative cancer cell lines by flow cytometry and confocal microscopy." (PMID 36499301, 2022). "HGF/c-MET-induced up-regulation of circCCDC66 expression promoted enrichment of renal cancer stem cells and accelerated the malignant process of cancer." (PMID 36698408, 2022). "They recently found that the inhibition of hepatocyte growth factor (HGF)/c-MET pathway, which is upregulated in PC and mediates the interaction between cancer cells and stromal PSCs, can limit primary tumor growth and eliminate metastasis." (PMID 35719926, 2022). "During the last few years, several trials and metanalyses have explored the role of c-MET deregulation as prognostic factor in different cancers, suggesting a correlation with worse survival outcomes." (PMID 36498560, 2022). "In our previous studies, TOPK was shown to be phosphorylated by Src and MET and to be a promising target for cancer therapy." (PMID 36167821, 2022). "In agreement with the findings from our isogenic system, we also observed greater ERK1/2 phosphorylation in MET-addicted cancer cells expressing METΔex14 (Hs746T/H596) vs. wildtype MET-amplified (H1993) cells." (PMID 35326531, 2022). "The active constituents of T. hemsleyanum are therefore promising candidates for improving the clinical activity of MET inhibitors and have the potential to improve survival rates and enhance therapeutic efficacy in human cancers." (PMID 35480115, 2022). "In GC, MET gene amplification and overexpression have been reported to correlate with cancer progression and poor prognosis." (PMID 35941699, 2022).
cancer (continued). "The latest NSCLC guideline 2021 V2 edition issued by the national comprehensive cancer network (NCCN) indicated that genes associated with targeted therapy of NSCLC include EGFR, KRAS, ALK, ROS1, MET, BRAF, RET, and NTRK." (PMID 35227278, 2022). "Here, we investigate crosstalk between Met and the EGFR family of RTKs using a panel of MET-amplified cancer cell lines as a model of Met-dependent cancers." (PMID 35249128, 2022). "RON and c-MET are coexpressed in many types of cancers, and cross-talking between c-MET and RON has been demonstrated." (PMID 35069735, 2022). "Analysis of gene expression profiles revealed that MET oncogene immunoreactivity is significantly higher in the progression of basal-like BC in humans than in other types of cancer." (PMID 36204232, 2022). "Based on these promising clinical results, FDA approved several RTKs (HER2 and MET) inhibitors in treating human cancers." (PMID 35372044, 2022). "Gene expression analysis of HER3-depleted cells identified MPZL3, encoding a single-pass transmembrane protein, as HER3-dependent effector in multiple MET-amplified cancer cell lines." (PMID 35249128, 2022). "Reciprocally, activation of the EGFR pathway in MET‐addicted cancer cells confers resistance to MET inhibitors." (PMID 36214609, 2022). "Crosstalk between Met and EGFR family RTKs is observed in many cancer cell lines derived from MET-amplified lung, gastric, esophageal and other cancers [recently reviewed in 2]." (PMID 35249128, 2022). "c-MET, a receptor for hepatocyte growth factor, has been reported to promote tumorigenicity in a variety of cancers." (PMID 36326232, 2022). "RON and MET are often co-expressed in cancer and crosstalk between the two receptors has been demonstrated." (PMID 35454943, 2022). "Cancers harboring high-level amplification of the MET gene, with more than five copies of MET for each copy of chromosome seven, have been known to enrich for response to Met inhibitors in the clinic." (PMID 35249128, 2022). "Their analysis did, however, find a positive correlation between higher expression of c-MET and later staging of cancer, and the presence of a PAX3/7-FOXO1 fusion protein." (PMID 36034555, 2022). "Previous studies have widely established that these oncogenic signatures play critical roles in promoting the invasiveness and metastasis of cancer cells, primarily through MET and integrin interactions." (PMID 36362038, 2022). "Because single amplification of MET rarely contributes significantly to cancer development, co-mutant of MET and other cancer drivers, such as EGFR, appear more commonly." (PMID 36619616, 2022). "For these reasons, the HGF/c-MET axis pathway is seen as a prospective target in various cancers and many small molecules and therapeutic monoclonal antibodies are being evaluated in preclinical and clinical trials." (PMID 35630066, 2022). "An effect of c-MET expression on neutrophils on the T cell effector functions was previously reported for CD8+ T cells in an experimental model of cancer, where the fitness of adoptively transferred CD8+ T cells in Mrp8;Metfl/fl mice was enhanced." (PMID 35041723, 2022). "Subsequently, HGF activated MET-dependent signaling and enabled cancer cells to resist tyrosine kinase inhibitors." (PMID 35814444, 2022). "PIM1 is an established oncogenic driver, and its inhibition was shown to re-sensitize cancer cells to radiotherapy as well as c-MET and ALK inhibition in NSCLC tumors." (PMID 35360705, 2022). "The genes observed in this network (CEACAM1, IGF1, MET, MMP1, MMP3 and WNT5A) were upregulated in cSII/III and are known to be linked to invasive properties in several other cancer types." (PMID 35022523, 2022). "Increased expression of MET contributes to cancer cell proliferation, invasion, and metastasis and is closely correlated with poor prognosis and radiotherapy resistance, which has been a prognostic biomarker and therapeutic target for various carcinomas." (PMID 35301291, 2022).
cancer (continued). "Studies have suggested the association of c-MET expression with expression of immunoregulatory molecules such as programmed cell death ligand (PDL-1) and indoleamine-2,3-dioxygenase (IDO) in cancer cells." (PMID 35081970, 2022). "In the case of c-Met in BC, it has been suggested that HGF/MET signalling is a mediator of resistance to anti-cancer immunotherapy, following the rationale of using anti-MET drugs in combination with immunomodulatory agents." (PMID 36498560, 2022). "Many studies have demonstrated that the aberrant activation of the MET pathway was closely related to the poor prognosis of cancer patients, making MET an attractive target for cancer therapy." (PMID 35408753, 2022). "Hyperactivation of HGF/MET signaling is shown to initiate epithelial–mesenchymal transition (EMT) phenomenon to promote metastasis via enriching cancer stem cells (CSCs) that contribute to chemoresistance." (PMID 35941699, 2022). "Several drugs targeting MET are under development for the treatment of different cancers, including non-small-cell lung cancer (NSCLC)." (PMID 35565287, 2022). "Oncogenesis driven by the signaling of HGF-induced MET/PI3K/AKT/c-MYC has been well-characterized in many different cancer types." (PMID 35941699, 2022). "In all experimental results, cancer cells expressing c-MET/ICAM-1/SRC together showed the highest malignancy, and p-SRC activity was also upregulated." (PMID 35487888, 2022). "Surprisingly, this computational analysis allowed us to identify in silico various critical players implicated in cancer processes, such as mTOR, BLM, MET, AMPK, and p130 (RBL2), as novel SMYD3 interactors." (PMID 35495117, 2022). "A number of recent studies have shown that the hepatocyte growth factor (HGF) and its receptor Mesenchymal epithelial transition factor (c-MET) influence the growth, survival, angiogenesis, and metastasis of cancer cells." (PMID 36034555, 2022). "EVs isolated from cancer patients’ body fluids have been shown to contain cancer-derived molecules such as truncated EGFRvIII, overexpressed MET, cancer-specific miRNAs and protein signatures and mutated DNA or mRNA fragments." (PMID 34811504, 2022). "Hepatocyte growth factor (HGF)/ MET signaling is known to be able to initiate the epithelial-mesenchymal transition (EMT), of which the association with cancer stem cell (CSC) generation has been established." (PMID 34974522, 2022). "Specifically, studies have shown that a range of cancer-related miRNAs are decreased in OS, inversely correlated with increased c-MET expression, and directly target the wild-type 3′-UTR of the MET gene." (PMID 36034555, 2022). "According to the database of COSMIC, the world's largest and most comprehensive resource for exploring the somatic mutations in human cancer, chromosome 7 included lots of well-known cancer-related genes, including EGFR, BRAF, CDK6, MET, T1F1, and so on." (PMID 35568828, 2022). "MET amplification is an important mechanism by which cancers develop resistance to epidermal growth factor receptor (EGFR) inhibitors and FGFRis, and a high MET GCN has been detected in 1–11% of NSCLCs." (PMID 35402233, 2022). "As a well-known and famous oncogene, MET plays an important role in cancer etiology, and there have been a few studies that have examined the high protein level of MET in Xp11.2 tRCC, including NONO-TFE3 tRCC." (PMID 35042525, 2022). "Targeting the HGF/MET signaling pathway has been a viable therapeutic strategy for various cancer types due to hyperactivation of HGF/MET axis occurs frequently that leads to detrimental cancer progression and recurrence." (PMID 35941699, 2022). "In summary, we revealed that DPP4, CTNNB1, and MET oncogenic signatures are overexpressed in THCA, and are associated with cancer progression, metastasis, resistance, poor disease-free survival, and unfavorable clinical outcomes." (PMID 35205190, 2022).